WDFY2 (WD repeat and FYVE domain containing 2)
Description:
Acts in an adapter protein-like fashion to mediate the interaction between the kinase PRKCZ and its substrate VAMP2 and increases the PRKCZ-dependent phosphorylation of VAMP2. Positively regulates adipocyte differentiation, by facilitating the phosphorylation and thus inactivation of the anti-adipogenetic transcription factor FOXO1 by the kinase AKT1. Plays a role in endosomal control of AKT2 signaling; required for insulin-stimulated AKT2 phosphorylation and glucose uptake and insulin-stimulated phosphorylation of AKT2 substrates (By similarity). Participates in transferrin receptor endocytosis.
Synonyms: Prof; WDF2; ZFYVE22
Tractability: PROTAC: its protein half-life has been measured.
Gene: Protein-coding gene on chromosome 13 (51,583,927 to 51,767,709, forward strand). Ensembl gene ENSG00000139668.
Subcellular location: Endosome; Early endosome; Cytoplasm
Subcellular location (Human Protein Atlas): Vesicles
Gene Ontology:
Molecular function: protein binding; metal ion binding
Biological process: positive regulation of fat cell differentiation; positive regulation of protein phosphorylation
Cellular component: early endosome; endosome; vesicle; cytoplasm
Genetic constraint (gnomAD): Loss-of-function variants: 28 observed, 49.4 expected, observed/expected ratio (o/e) 0.57, 90% interval 0.42 to 0.78. The upper end of that interval is the gene's LOEUF score, 0.78, which puts it in group 3 of 6, group 1 being the genes least tolerant of losing a copy. Missense variants: 404 observed, 495.57 expected, observed/expected ratio (o/e) 0.82, 90% interval 0.75 to 0.88. Synonymous variants: 168 observed, 182.8 expected, observed/expected ratio (o/e) 0.92, 90% interval 0.81 to 1.04.
Homologues: Orthologues: chimpanzee WDFY2 (99% identical), guinea pig WDFY2 (98% identical), mouse Wdfy2 (98% identical), rat Wdfy2 (98% identical), rabbit WDFY2 (98% identical), macaque WDFY2 (97% identical), dog WDFY2 (96% identical), pig WDFY2 (88% identical), tropical clawed frog wdfy2 (86% identical), zebrafish wdfy2 (84% identical), Drosophila melanogaster Wdfy2 (50% identical), Caenorhabditis elegans wdfy-2 (42% identical), and 3 more. Paralogues in human: WDFY1 (62% identical), GGA1 (16% identical), GGA3 (16% identical), GGA2 (15% identical), TOM1L2 (15% identical), TOM1 (14% identical), STAM (11% identical), HGS (10% identical), STAM2 (10% identical), TOM1L1 (10% identical).
Diseases named in the same sentence as WDFY2 in open-access papers:
WDFY2 is named in the same sentence as 18 diseases in open-access papers, as found by Europe PMC text mining. Sharing a sentence is not in itself a finding about the gene and the disease. The quoted sentences say what the papers report.
ovarian carcinoma (3 papers, 2014 to 2021). A malignant neoplasm originating from the surface ovarian epithelium. "Recently, a new role of WDFY2 in cancer regulation is emerging; in fact, a CDKN2D-WDFY2 fusion transcript encoding a shorter WDFY2 protein was frequently found in ovarian cancer samples and associated with a deregulated expression of members of the PI-3K/AKT pathway." (PMID 31789342, 2019). "WDFY2 is an important regulator of AKT phosphorylation, and thus might represent a promising target in the diagnosis and treatment of ovarian cancer." (PMID 34381020, 2021).
breast carcinoma (2 papers, 2019 to 2020). "Constitutional genes with increased breast cancer relapse risk were claudin 15, WDFY2, golgin A4, DOCK4 while HCG27 and PLAC8L1 were among 18 signature signs not endorsed by prognostic index score." (PMID 33106505, 2020). "Lastly, the prognostic potential of WDFY2 expression in a large cohort of breast cancer patients was evaluated." (PMID 31789342, 2019). "We also analysed an additional RNA-seq dataset from different subtypes of breast cancers (ER+ and TNBCs) in comparison with the adjacent normal tissues, highlighting a significant reduction in WDFY2 in ER+ but not in TNBCs." (PMID 31789342, 2019).
metastatic cancers (2 papers, 2019 to 2021). A carcinoma which has spread from the original site of growth to another anatomic site. "WDFY2 is frequently lost in metastatic cancers, most predominantly in ovarian and prostate cancer." (PMID 31253801, 2019). "Protein WDFY2 (WD Repeat and FYVE Domain Containing 2) is frequently lost in metastatic cancers (e.g. ovarian and prostate cancers)." (PMID 34706732, 2021).
acute myeloid leukemia (1 paper, 2019). Acute myeloid leukemia (AML) is a group of neoplasms arising from precursor cells committed to the myeloid cell-line differentiation. "An extended comparison done with the GEPIA online tool confirmed that WDFY2 expression is significantly reduced in different cancer types (acronyms in green font) with the only exception of Acute Myeloid Leukemia (LAML, red font) where an opposite effect is visible." (PMID 31789342, 2019).
diabetes (1 paper, 2019). "WDFY2 overexpression can increase adipogenesis, which may play a role in metabolic disorders such as diabetes in humans." (PMID 30056651, 2019).
kidney cancer (1 paper, 2019). Primary or metastatic malignant neoplasm involving the kidney. "WDFY2 amplifications (red columns), also generally rare, were relatively more frequent in bowel, oesophagus/stomach and kidney cancer samples." (PMID 31789342, 2019).
metastatic tumors (1 paper, 2019). "WDFY2 is frequently lost in metastatic tumors, but it is not known if there is a direct link between loss of WDFY2 and the metastatic potential of tumor cells." (PMID 31253801, 2019).
prostate tumour (1 paper, 2019). "In prostate tumour tissues, a WDFY2 down-regulation has been highlighted and correlated with advanced stage, increased metastasis and poor prognosis in patients, being AKT signalling modulation the mechanism adopted by WDFY2 protein to inhibit cancer progression and metastasis." (PMID 31789342, 2019).
schizophrenia (1 paper, 2017). A major psychotic disorder characterized by abnormalities in the perception or expression of reality. "WDFY2 is not directly associated with BD, but its product interacts with AKT1, which has been found involved in BD and schizophrenia." (PMID 29257106, 2017).
cancer (4 papers, 2014 to 2024). A tumor composed of atypical neoplastic, often pleomorphic cells that invade other tissues. "The genetic events involving WDFY2 (71,088 samples from a panel of 234 different cancer studies) comprise deep deletions, mutations, amplifications and fusions." (PMID 31789342, 2019). "In conclusion, this work confirmed the p63-dependent regulation of the endosomal WDFY2 protein, providing new clues for deciphering the downstream molecular pathways that are implicated in cancer regulation and limb development." (PMID 31789342, 2019). "The loss of WDFY2 in cancer cells could enable them to migrate through the ECM and provide a higher metastatic potential, which correlates well with the finding that WDFY2 is frequently lost in cancers." (PMID 31253801, 2019). "A screen of the cBioportal cancer genome database shows that WDFY2 is frequently (in up to 14% of cases) lost in cancers 37,38." (PMID 31253801, 2019). "By considering WDFY2 as a p63 effector, potentially involved in cancer regulation, we investigated WDFY2 alterations in tumours." (PMID 31789342, 2019). "Furthermore, impeding VAMP3 recycling with WDFY2 diminishes the secretion of matrix metalloproteinases by cancer cells, necessary for remodeling the extracellular matrix." (PMID 38802855, 2024). "We then evaluated WDFY2 expression in human cancers (i.e., lung, breast, kidney and head and neck)." (PMID 31789342, 2019). "Interestingly, to confirm that WDFY2 belongs to the p63 network of cancer regulation, we analysed the impact of WDFY2 alterations, by showing its frequent deletion in different types of tumours and suggesting its expression level as a prognostic biomarker." (PMID 31789342, 2019). "To probe the functional differences of short WDFY2 versus wildtype WDFY2 on signaling pathways, we performed reverse phase protein arrays (RPPA), which provides a means to quantitatively assess the levels of 130 cancer-associated proteins using 163 distinct antibodies." (PMID 24675677, 2014). "We thus decided to evaluate WDFY2 genetic alterations, expression and prognostic significance using cancer patients’ data from different portals (cBioPortal, TCGA Consortium, GEPIA and KM Plotter), consistently supporting this newly identified role of WDFY2." (PMID 31789342, 2019). "Although the function of WDFY2 gene has been poorly defined, some pieces of evidence are recently linking WDFY2 protein to PI3K/AKT signalling transduction pathway that play a key role in cancer tumour progression." (PMID 31789342, 2019). "The observation that lack of WDFY2 enhanced MT1-MMP secretion led us to speculate that this increased secretion could contribute to the metastatic potential of cancer cells." (PMID 31253801, 2019).
tumor (4 papers, 2014 to 2023). "Taken collectively, despite the heterogeneous nature of these patients’ data, the results suggest a role for WDFY2 as a tumour suppressor gene and the possible assessment of its expression level as a new prognostic biomarker." (PMID 31789342, 2019). "The genomic breakpoint was identified in intron 1 of CDKN2D and intron 2 of WDFY2 in patient tumor, providing direct evidence that this is a fusion gene." (PMID 24675677, 2014). "WDFY2 is known as a tumour suppressor but its function is unclear." (PMID 31253801, 2019). "Several lines of evidence suggest that WDFY2 can act as a tumor suppressor." (PMID 31253801, 2019). "We propose that WDFY2 acts as a tumor suppressor by serving as a gatekeeper for VAMP3 recycling." (PMID 31253801, 2019). "Here, the authors show that WDFY2 interacts with the v-SNARE VAMP3, leading to a suppression of the metalloprotease MT1-MMP secretion, suggesting that WDFY2 acts a tumour suppressor by suppressing MT1-MMP secretion." (PMID 31253801, 2019). "Lastly, WDFY2 was also shown to interact with endosomal Liver Kinase B1 (LKB1) protein and to participate in controlling its activity on the regulation of epithelial polarity and architecture; interestingly, the lack of this interaction endows LKB1 with tumour-promoting activity." (PMID 31789342, 2019).
neurodegenerative disease (1 paper, 2022). A disorder of the central nervous system characterized by gradual and progressive loss of neural tissue and neurologic function. "The ‘Human UP’ genes include FOXP2, MTRNR2L8, DHX40, VPS13B, WDFY2 and PURB, all of which are associated with neurodevelopment or neurodegenerative disease." (PMID 36052683, 2022).
WDFY2 also shares sentences with these, for which no sentence is quoted: serous ovarian cancer (3 papers); prostate carcinoma (2); bladder cancers (1); Insulin resistance (1); metabolic disorders (1); oral squamous cell carcinoma (1).